CD44 (CD44 molecule (IN blood group))
Diseases named in the same sentence as CD44 in open-access papers (continued):
Sharing a sentence is not in itself a finding about the gene and the disease.
tumor (continued). "Both CD44+ and CD24– have been used as specific markers to identify the BCSCs from human tumor tissues." (PMID 24331293, 2013). "Heterogeneous populations, including candidate CSC, are present in the MPE- tumor population, as reflected by the variable expression of CSC-biomarkers: c-MET, uPAR, MDR1, CD166, CD44, and ALDH." (PMID 24019906, 2013). "Briefly, 13 days after the injection of 1×103 CD44+/CD24-/low cells, a palpable tumor formed in one of six mice." (PMID 23799994, 2013). "The primary orthotopic tumour weight was increased by 2.2, 2.1 and 6.2-fold in TP53INP1, LATS2 and CD44 silenced MIA PaCa-2 cells, respectively." (PMID 23857777, 2013). "In our study, when Bmi1 expression was silenced in the CD44+CD24+ESA+ pancreatic CSC population, both in vitro CSC propagation and in vivo tumor growth were significantly inhibited." (PMID 23437065, 2013). "In our study, we also observed rapid tumor growth following implantation of CC531, suggesting that such extensive expression of CD44 in vivo is one feature demonstrating the ‘aggressive’ phenotype of this cell line." (PMID 23385555, 2013). "We demonstrate that the repression of CD44 by BXL0124 contributes to the inhibition of STAT3 signaling and tumor invasion in MCF10DCIS cells." (PMID 23326564, 2013). "As a consequence, the CD44+CD117+CSCs cultured in the 3D BME scaffold for 6 days actively exhibited their proliferative potential, which suits researcher to investigate the tumor biological properties during the days." (PMID 23368632, 2013). "Immunostaining of the cancer stem cell markers in tumor cells revealed positivity for CD133, CD44, and EpCAM in the CLC." (PMID 23192764, 2013). "The anti-migratory effect of rFKBPL also showed a dependency on CD44 expression in PC3 cells transfected with CD44 targeted siRNA, indicating that FKBPL/AD-01 can mediate anti-migratory effects in tumour cells by targeting CD44." (PMID 23457460, 2013). "As for BC0244 xenograft tumor cells, 83.8% and 54% of IGF1Rhi were CD24--CD44+and ALDH+, respectively, as compared with 48.7% and 31.9% of IGF-1Rlo cells, respectively." (PMID 23663564, 2013). "This analysis also demonstrated that focal adhesion kinase (FAK) and the stem cell marker CD44 may also be likely therapeutic targets in IBC based on their levels of amplification in the pre-clinical models of IBC that recapitulate the formation of tumor emboli." (PMID 24102046, 2013). "‘CD44’ has a variety of biological functions such as cell-cell, cell-ECM interactions, tumour cell migration or even chemoresistance." (PMID 23151220, 2012). "Recently, it was reported that lipid-raft-associated CD44 is required for the survival of CSCs in the suspension condition through CD44-SFK-integrin signaling, leading to tumor metastasis." (PMID 22253629, 2012). "Whereas only 0.01% of the bulk tumor cells were capable of seeding tumor growth in NOD/SCID mice, 0.5% of the CD44+CD24−/low: Lineage− fraction was able to engraft and give rise to tumors." (PMID 22470504, 2012). "In this critical review, we assess the role of CD44 and CD24 in tumour initiation, development, and metastasis." (PMID 22693526, 2012). "Given the wide expression of integrins and CD44, both cancer cells as well as stromal compartment are targeted by OPN in the tumor mass." (PMID 22444159, 2012). "In CD44- or CD147-KD xenografts treated with VC or DTX, we found a comparatively dispersed tumor structure, with evidence of scattered targeted areas." (PMID 22870202, 2012). "The individual expression of CD44, CD24, ABCG2, and EpCAM in primary tumor samples ranged from 19% to 64%, 15% to 77%, 2% to 7%, 4% to 65%, respectively." (PMID 22328825, 2012).
tumor (continued). "R2d cells have the characteristic of CD44 and Oct-4-positive, and its parent, M13SV1R2 has the ability to develop tumor, self-renewal, resistance to drugs and apoptosis." (PMID 22905168, 2012). "Both ALDH expression and CD44 and CD24 expression were positively correlated with xenograft formation in NOD/SCID mice, with both populations being equally capable of tumor initiation." (PMID 24213498, 2012). "The number of apoptotic cells (TUNEL-positive) and caspase-3 (active) positive cells in PC-3M-luc-CD44/CD147-KD tumors also increased, consistent with tumor regression being related to reduced cancer cell proliferation and apoptosis." (PMID 22870202, 2012). "On the other hand, since a single CD44+ CRC cell can form a sphere in vitro with stem cell features, and generate a xenograft tumor in vivo with the properties of the original tumor, CD44 was proposed as a robust marker for colon CSCs." (PMID 22895640, 2012). "The co-expression of EpCAM+CD44+, EpCAM+CD24+, and EpCAM+ABCG2+ ranged from 0.83% to 42.6%, 0.65% to 41.4%, and 1.6% to 6.5%, respectively, in the eight RB tumor samples." (PMID 22328825, 2012). "First, it was demonstrated that CD44+, CD24+ and ESA+ (EpCAM+) positive PDAC cancer cells show stem cell properties and enhanced tumor initiating capacity compared to bulk tumor cells." (PMID 23094026, 2012). "Although the increase in CD44 expression in hypoxic tumor environments of MDA-MB-231 tumors was significantly higher, it occurred within the backdrop of an already high CD44 expression." (PMID 22937154, 2012). "CD44+ and CD133+ cells comprised substantial subpopulations (median 5.8–16.1%) of CD117+/cytokeratin+ cells in both tumor and normal samples, whereas CD90+ cells were less prevalent (median 0.2–2.3%)." (PMID 23285214, 2012). "Used capture and detection antibodies can recognize exosome-specific markers (Rab5, CD63 and CD9), melanocyte-specific proteins (MelanA, MCAM, Tyrosinase) and tumor markers (CEACAM, CD44)." (PMID 26082068, 2012). "The main finding of this study is the demonstration of a distinct phenotype of tumor cells (CA125+++EpCAM+++/STAT3+++), as well as stromal cells (CD44+++/Oct4+++) isolated from the ascites of a limited number of CR patients (n = 4)." (PMID 23056490, 2012). "An association between metastasis status and a high prevalence of certain markers including CD44+/CD24−/low, ESA+, CD133+, C-X-C chemokine receptor type 4 (CXCR4)+ and PROCR+ in primary tumor cells was also found." (PMID 24977105, 2012). "In their study the injection of CD44+ and EpCAMhi cells, into NOD-SCID mice, reproduced a tumor xenograft phenotypically similar to parental one." (PMID 24212791, 2011). "We assessed changes of CD44+/CD24− and ALDH1+ tumour cell populations before and after PST in the 79 patients who did not achieve pCR." (PMID 21559013, 2011). "A recent study demonstrated that Bmi-1 mRNA and protein overexpressed in a subpopulation of tumor initiating cells in CD44+ HNSCC, which possessed self-renewal and tumor formation ability." (PMID 20936121, 2011). "CD44+/Tomato+ EOC cells were injected into nude mice, and the established tumor (60 days later) was evaluated for CD44 and Tomato." (PMID 21904548, 2011). "The abundant expression of RHAMM and the redistribution of CD44 upon treatment in xenograft tumours are therefore in line with the proposed role of RHAMM and CD44 in transducing the effects of HA in this model." (PMID 21429221, 2011). "Prince and co-workers published the first report with evidence of CSCs in HNC when they identified a CD44+ population from primary human head and neck cancers that was tumorigenic in nude mice, could be serially passaged, and recapitulated the heterogeneity of the original human tumor." (PMID 24212622, 2011).
tumor (continued). "Metformin treatment was found to specifically eliminate CD44+/CD24−/low CSCs and had a synergistic effect with doxorubicin, which resulted in reduced tumor burden and delayed tumor recurrence and was more effective than either agent alone." (PMID 22203527, 2011). "Blocking CD44- hyaluronan polymer binding by the use of anti-CD44 antibodies or hyaluronan oligomers suppressed the PI3K/Akt signaling pathway, inhibiting anchorage-independent tumor cell growth." (PMID 22295219, 2011). "As a population, Vimentin+CD44+CD133+ cells represented approximately only 0.3, 0.4 and 5% of the total sorted tumor cell population for the DU145, PC3 and LNCaP lines, respectively." (PMID 24212937, 2011). "In summary, given the facts that the expression of CD44 and vimentin correlate with EMT in cancer cells, and with tumor angiogenesis, our findings provide rationale for further functional studies on the role of these proteins in EMT and angiogenesis." (PMID 22216242, 2011). "All examined xenograft tumors revealed very small overlap between CD44+/CD24+ and ALDHhigh or ALDHlow cell populations, representing 0.015% and 0.11% respectively, of all viable, human tumor cells." (PMID 21695188, 2011). "In comparisons of putative CSC populations before and after PST, the proportions of CD44+/CD24− and ALDH1+ tumour cells were significantly increased after PST." (PMID 21559013, 2011). "In Kaplan–Meier survival analyses, the patients with increased CD44+/CD24− and ALDH1+ tumour cell populations had a significantly shorter DFS times than the remaining patients (P=0.043 and 0.041, respectively)." (PMID 21559013, 2011). "Both CD44+/CD24− tumour cell proportions and grades of ALDH1+ tumour cells significantly increased after PST (P=0.013 and P=0.018, respectively)." (PMID 21559013, 2011). "In 92 pre-chemotherapy biopsy tissues, median values of CD44+/CD24− and ALDH1+ tumour cell proportions were 5% (range, 0–95%) and 0% (0–80%), respectively." (PMID 21559013, 2011). "ALDH1 was also found to co-localize with other CSCs-related markers, including MMP-9, CD44, and CK14, at the invasive front of the tumor." (PMID 20936121, 2011). "We also investigated the relationships of the changes of CD44+/CD24− and ALDH1+ tumour cell population after PST with DFS." (PMID 21559013, 2011). "CD44 and CD24 have previously been identified as pancreatic CSC markers and represent a very small percent of the population of all tumor cells (0.1%)." (PMID 21695188, 2011). "Knockdown of CD44 in several other PCa models including PC3, LAPC4, and LAPC9 also significantly inhibits tumor development and/or metastasis." (PMID 21935404, 2011). "Flow cytometry analysis of the dissociated and immunomagnetically sorted (MACS-hEpCAM) mice tumor xenografts confirmed the presence of a minor population (about 4%) of human cancer cells with high combined expression of the CD133 and CD44." (PMID 20630067, 2010). "Seven days after injection, the tumor was excised, and the tumor cells were stained with anti-CD24 and -CD44 antibodies." (PMID 20950440, 2010). "In patients with HER2-positive tumours receiving the epidermal growth factor receptor (EGFR)/HER2 inhibitor lapatinib in an adjuvant setting, a decrease in CD44+/CD24−/low cells and tumour mammosphere-forming efficiency was observed." (PMID 20145614, 2010). "Flow cytometry for CD44 and epithelial-specific antigen (ESA) expression, colony morphology, tumour sphere formation and rapid adherence assays were used to identify the subset of cells with stem-like properties." (PMID 20426848, 2010). "Functional interactions between CD44 and MDR1 are increasingly being recognised as important in tumour metastases." (PMID 20736947, 2010). "Ten days after transfer, the CD4+ T cells and CD8+ T cells were isolated from tumor mass and analyzed for their expression of surface activation marker CD62L and CD44." (PMID 20981279, 2010).
tumor (continued). "CFSE-stained cells found in the tumor draining lymph nodes on day 3 were 30% CD8+, 72% CD4+, 95% CD44+, and 39% CD69+." (PMID 21050466, 2010). "CD44+/CD24- cells comprised an average of 0.25% (N = 2) from primary tumors and 16.4% (N = 4) from tumor derived sphere culture, a 65-fold increase." (PMID 20615238, 2010). "CD44 binds to hyaluronic acid (HA), major components of the extracellular matix (ECM) and CD44 is important in tumor progression and metastasis." (PMID 20374665, 2010). "TCRα chains were amplified from naive CD44−CD62L+Foxp3GFP-, activated/memory CD44+CD62L−Foxp3GFP- and Foxp3GFPlo and Foxp3GFPhi Treg CD4+ cells sorted from control and draining lymph nodes and tumor infiltrate." (PMID 21049016, 2010). "It is noteworthy that putative cancer stem cells expressing the combined CD44+/CD24−/low/ALDH1+ phenotype showed an especially high tumourigenic capacity, being able to form tumours from as few as 20 cells." (PMID 20010944, 2010). "After 4 weeks, the analysis of luciferase activity indicated that cells in the CD24−/low/CD44+ populations of HCC1954-Luc and MCF7-Luc generated significantly larger tumours than the control populations (P<0.05)." (PMID 19997106, 2010). "These CD44+/CD24+/EpCAM+ cells presented self renewal capacity, tumor initiation and up-regulated of the Hedgehog signaling pathway." (PMID 24281178, 2010). "FACS analysis showed that tumor cells with GDF3-expressing vector contained more CD24 and CD44 double-positive cells than those transfected with the empty vector." (PMID 20950440, 2010). "Propagation of spheres from tumor tissue or directly from the cell line enriched for ALDH activity and CD44+/CD24- markers and expression of EMT markers as well as genes that promote stem cell survival." (PMID 20615238, 2010). "More significantly, we show that miR-34 restoration led to an 87% reduction of the CD44+/CD133+ CSC, accompanied by significant inhibition of tumorsphere growth in vitro as well as tumor formation in vivo." (PMID 19714243, 2009). "These two types of tumor cells share the common marker CD44+, but they can be distinguished by other well-defined markers including ABCG2+ and α2β1+, which are specific for tumor progenitors." (PMID 20052382, 2009). "We identified that CD44+/CD133+ MiaPaCa2 cells are enriched with tumorsphere-forming and tumor-initiating cells or cancer stem/progenitor cells with high levels of Notch/Bcl-2 and loss of miR-34." (PMID 19714243, 2009). "miR-34a restoration resulted in an 87% reduction of the CD44+/CD133+ cells, accompanied by significant inhibition of tumorsphere growth in vitro as well as tumor formation in vivo." (PMID 19714243, 2009). "More significantly, miR-34 restoration inhibits the CD44+/CD133+ tumor-initiating cells or CSC, accompanied by significant inhibition of tumorsphere growth in vitro and tumor formation in vivo." (PMID 19714243, 2009). "Colocalisation of uPA and CD44, uPA and MDR1, CD44 and MDR1 was further tested in primary tumours and matched metastatic lesions (n=40)." (PMID 19603017, 2009). "There was an association between metastasis status and a high prevalence of certain markers including CD44+/CD24−/low, ESA+, CD133+, CXCR4+ and PROCR+ in primary tumor cells." (PMID 20027313, 2009). "Analysis of surface markers during long term tumor culture of primary HBCEC (more than 476d) demonstrated a prominent expression of CD24, CD44 and MUC1 (CD227)." (PMID 19751512, 2009). "The expression of uPA, CD44 and MDR1 was quite uniform in most tumours, and regions of heterogeneous staining were rarely seen." (PMID 19603017, 2009). "The primary tumours from patients with uPA, CD44 and MDR1-positive metastatic lesions also expressed uPA, CD44 and MDR1." (PMID 19603017, 2009). "Five potential novel target genes (FABP5, CD24, CD44, CD74, and HSP27) were identified, which were highly expressed in HNSCC tumor samples and tissue arrays." (PMID 19602232, 2009).
tumor (continued). "We have also identified that CD44+/CD133+ MiaPaCa2 cells are enriched with tumorsphere-forming and tumor-initiating cells or CSC with high levels of Notch/Bcl-2 and loss of miR-34s." (PMID 19714243, 2009). "CD44+CD24− cells form colonies in soft agar and form tumours in NOD/SCID mice when as few as 100 cells are injected." (PMID 18268494, 2008). "Thirteen percent (30/240) of the tumors were positive for more than one of the CD44+/CD24-, CD44-/CD24+ and CD44+/CD24+ phenotypes, with 5% (11/240) displaying tumor cells of all three phenotypes." (PMID 18559090, 2008). "In particular, bikunin represses cell-bound plasmin activity and is thought to inhibit CD44 dimerization and suppress the MAP kinase signalling cascade, thus preventing ECM degradation, tumor cell invasion, and angiogenesis." (PMID 18226209, 2008). "Standard CD44, lacking all alternative exons, is predominantly express in normal tissues, whereas CD44 isoforms, in particular those containing variant exons v5, v6 and v7, are over-expressed in various tumors and have been implicated in tumor cell invasion and metastasis." (PMID 19516963, 2008). "Of note, tumor heterogeneity can result from a single cell, as lentiviral transduction studies show that both ESA+CD44− (i.e. NTG) and ESA+CD44+CD166+ (i.e. CoCSC) cells have identical lentiviral insertion sites, but only CoCSC are able to propagate tumors." (PMID 18560594, 2008). "CD44+/CD24- cells were detected in 31% of the tumors, ranging in proportion from only a few to close to 100% of tumor cells." (PMID 18559090, 2008). "As the CD44+CD24− LNCaP cells formed colonies in soft agar with high efficiency, we compared the ability of the CD44+CD24−, CD44+CD24−-depleted cells, and total LNCaP cells to initiate tumours in NOD/SCID mice." (PMID 18268494, 2008). "Overexpressed in a number of epithelial tumors and suggested to be an important prognostic marker of tumor progression, CD166 (i.e. ALCAM) appears to further segregate TG from NTG cells when used in combination with ESA and CD44." (PMID 18560594, 2008). "Pearson test showed a significant and inversely proportional correlation between CD44 expression and the number of lymphatic vessels with VEGFR-3 in malignant infiltrating tumours." (PMID 17222331, 2007). "CD44, a hyaluronate receptor, is involved in cell migration through the ECM, which can be viewed as highly relevant for tumour invasion and metastasis." (PMID 15870832, 2005). "In a univariate analysis including tumour stage, age, histology, N-MYC amplification, CD44 and TRKA expression, all parameters had significant prognostic value." (PMID 9099963, 1997). "FABP4 and vimentin expression was increased in proximity to the tumor, while caveolin-1, CD44, MMP9, and adiponectin showed minimal or no changes." (PMID 41596770, 2026). "Consistent with experimental models, liver tissues from MASLD patients with hepatic metastases exhibited significant upregulation of MIF in non-tumoral parenchyma and CD44 expression in tumor cells." (PMID 41545340, 2026). "Regarding the expression of luminal and basal biomarkers, Layer3.1 tumor presented higher expression of KRT20, a luminal-papillary biomarker, whereas Layer3.2 had higher expression of KRT5, KRT6a, KRT14, and CD44 basal biomarkers, but also PGM5, DES, and SGCD luminal-infiltrated biomarkers." (PMID 41516353, 2026). "Cellular uptake and cytotoxicity were significantly enhanced in TNBC cell lines expressing high CD44 levels, where DOX-loaded FNPs disrupted glycolytic and oxidative phosphorylation pathways, leading to tumor cell death, reduced invasiveness, and inhibition of mammosphere formation." (PMID 41489768, 2026).